TNF (tumor necrosis factor)
Diseases named in the same sentence as TNF in open-access papers (continued):
Sharing a sentence is not in itself a finding about the gene and the disease.
diabetes (2,267 papers, 2003 to 2026). "This visual confirmation strengthened the link between TNF-α promoter variants and increased diabetes risk." (PMID 41268160, 2025). "IL-6 and TNF-α have been implicated in the increased risk of developing type 2 diabetes mellitus and atherosclerosis and exhibit an inverse relationship with adiponectin levels." (PMID 39857920, 2025). "For example, adipocytes are cells with high metabolic activity that produce adipokines such as C-reactive protein, tumour necrosis factor alpha (TNFα) and interleukin-6 (IL-6), which increase the risk of diabetes and cardiovascular disease." (PMID 40142230, 2025). "Elevated TNF-α levels have been correlated with higher HbA1c levels and increased risk of diabetes-related complications." (PMID 40218134, 2025). "Despite low between-study heterogeneity, inflammation biomarkers (e.g., TNF-α) were implicated in diabetes-induced male infertility." (PMID 41334449, 2025). "The evaluation of markers, such as interleukin-1, IL-6, CRP and TNF-α, is essential for investigating the association between periodontitis and diabetes mellitus." (PMID 40667952, 2025). "In the field of diabetes research, under conditions simulating diabetes (high glucose and TNF-α treatment), the association level between mtRNA and chromatin in human umbilical vein endothelial cells (HUVECs) increases." (PMID 40959271, 2025). "Diabetes has been linked to elevated levels of plasma TNF, IL-1b, interleukin 6 (IL-6), interferon-g (IFNg), and PAI-1, as well as changes in immune cell responses, resulting in chronic low-grade inflammation." (PMID 40283013, 2025). "Diabetes is associated with persistent low-grade inflammation, characterized by elevated levels of proinflammatory cytokines such as IL-1β, IL-6, and TNF-α." (PMID 41438123, 2025). "In the current study, we found that diabetes impaired macrophage lipid metabolism during liver IR and caused more severe aseptic inflammation (TNF‐α, IL‐1β, IL‐6, and IL‐18)." (PMID 40778489, 2025). "The increased expression of IL-1β and TNF-α has been linked to the development of microvascular damage and complications resembling those of diabetes mellitus in animal models." (PMID 40002398, 2025). "In previous studies of CHF and diabetes patients, depressive symptoms were associated with higher levels of the proinflammatory cytokines TNF‐α, IL‐6, and CRP, and lower levels of the anti‐inflammatory cytokines IL‐10 and ADPN." (PMID 40700022, 2025). "This meta-analysis suggests that the overall risk of type 2 diabetes mellitus is strongly associated with elevated levels of inflammatory cytokines, specifically tumor necrosis factor-α, and low levels of adiponectin." (PMID 41155523, 2025). "Genotype and allele frequencies for TNF-α polymorphisms rs1800629 (-308G>A) and rs361525 (-238G>A) across the samples and their association with type 2 diabetes mellitus during present study." (PMID 41268160, 2025). "This study also further explored the independent risk factors for LFCN injury and found that diabetes, patient body mass index (BMI), and early postoperative levels of IL-6 and TNF-α were closely related to LFCN injury." (PMID 40236989, 2025). "In consistent with our mechanism of interest: diabetes associated inflammation, there was inter-hepatocytic infiltration of inflammatory cells, and upregulation of TNF-alpha expression level with immunohistochemistry." (PMID 39905472, 2025). "In a rodent model of diabetes, rats with 6 weeks of glucose fluctuation had higher mRNA expression of IL-1β, TNF-α, and abnormal expression of apoptosis-associated genes in the hippocampus." (PMID 40445939, 2025). "Increased levels of TNF-α have also been found in plasma, serum, vitreous humor, and platelets of patients with diabetes, and these increases in plasma and serum are associated with “worse” DR." (PMID 40332476, 2025).
diabetes (continued). "Sitagliptin effect on diabetes-associated inflammation was assessed by measuring cardiac levels of IL-1β, TNF-α, and CRP, which were significantly elevated (p ≤ 0.001) in diabetic rats." (PMID 40867548, 2025). "The TNF‐α -promoter polymorphisms rs1800629 (−308G>A) and rs361525 (−238G>A) have been variably associated with type 2 diabetes mellitus (T2DM) risk in different populations." (PMID 41268160, 2025). "Research indicates that serum protein ACRP-30 plays a significant role in the regulation of diabetes mellitus, while TNF-α is a principal pro-inflammatory mediator implicated in insulin resistance." (PMID 40141412, 2025). "According to these results, TNF‐α contributes to the pathophysiology of beta cell loss and diabetes progression." (PMID 40903907, 2025). "For the AG genotype of TNF-α-238 G/A, a six-times higher risk for a family history of diabetes mellitus compared to other examined aspects of family history was found (p = 0.02)." (PMID 40565595, 2025). "Low testosterone levels are associated with increased cardiovascular risk factors, mortality, diabetes, and specifically with increased levels of TNF‐α or other inflammatory mediators." (PMID 40313012, 2025). "Married status was associated with lower levels of IL-1β, and diabetes was associated with lower levels of TNF-α." (PMID 38459460, 2024). "The increased secretion of IL-6 is also known to be a response to increased TNF levels and both TNF and IL-6 have been shown to be present in higher concentrations in children with diabetes or risk factors for diabetes." (PMID 38396488, 2024). "While diabetes, particularly in poorly controlled cases, is associated with elevated inflammatory markers like IL-6 and TNF-α, the impact on implant survival appears to be minimal when glycemic levels are well-regulated." (PMID 39867008, 2024). "Risk factors include diabetes, aging, long-term corticosteroid use, tumor necrosis factor-alpha (TNF-α) blockers, vitamin D receptor polymorphisms, and polymorphisms in the IL-12 and IFN-γ genes." (PMID 39347312, 2024). "Anti-inflammatory treatments, including minocycline or baicalein, attenuate the upregulation of IL-1β and TNF-α and confer retinal protection in animal models of diabetes as demonstrated by reductions in neuronal loss, capillary loss, and vascular leakage." (PMID 40603568, 2024). "The only significant difference observed at the baseline assessment between the groups was that patients in married had lower levels of IL-1β (P = 0.01), and diabetes was associated with lower levels of TNF-α (P = 0.04)." (PMID 38459460, 2024). "Nevertheless, the authors did note a significant reduction in TNF-α and fasting plasma insulin, which have both been posited as mediators in numerous diabetes-associated complications." (PMID 38844885, 2024). "Inflammatory mediators (IL-1, IL-6, IL-8) and tumor necrosis factor (TNF-ɑ) associated with diabetes are released into the oral tissues." (PMID 39446189, 2024). "Elevated TNF-α leads to the development of glomerulosclerosis and tubulointerstitial fibrosis, and is implicated in the progressive renal dysfunction in diabetes." (PMID 38893645, 2024). "It is associated with various cytokines, including TNF‐α and IL‐6, which are linked to diabetes development." (PMID 39035847, 2024). "Combining the administration of the two hydrogels in the PDCM group led to a significant decrease in IL-6 and TNF-α cytokines at the gingival level in periodontal disease associated with diabetes mellitus." (PMID 39062018, 2024). "Diabetes is frequently associated with elevated levels of inflammatory cytokines (e.g., TNF-α, IL-1β, and IL-6) and AGEs, which have been linked to the pathophysiology of both diabetes and OA." (PMID 39139325, 2024). "TNF-α antagonism has also been shown to reduce the incidence of DM in these patients by nearly halving the risk of diabetes." (PMID 38842591, 2024).
diabetes (continued). "The interplay between the CXCR1/2 pathway and TNF-α is pivotal in understanding the mechanisms underlying IR and inflammation in diabetes." (PMID 39627194, 2024). "Elevated levels of high-sensitivity CRP, IL-6, and TNF-α were positively associated with the risk of microvascular complications in patients with diabetes." (PMID 39170741, 2024). "The ameliorative effect of ST on diabetes-associated inflammation was explored via the determination of hepatic IL-1β, IL-18, and TNF-α levels." (PMID 38131990, 2023). "Regarding diabetes and biotics, studies of patients receiving TNF-α antagonists had a lower risk of new diabetes compared with those receiving other drugs, with an adjusted diabetes risk ratio of 0.62 (95%CI: 0.42–0.91)." (PMID 38029150, 2023). "Other studies have found that patients with underlying diabetes or metabolic syndrome receiving anti-TNF-α therapy exhibit improved insulin resistance." (PMID 38029150, 2023). "The presence of TNF-alpha polymorphisms has been linked to a variety of ailments, such as rheumatoid arthritis, types 1 and 2 diabetes, ankylosing spondylitis, sarcoidosis, and silicosis." (PMID 36622512, 2023). "While factors such as glucotoxicity and the production of advanced glycated end products have been implicated in the neurotoxic pathogenesis of diabetes, the significance of TNF-α in neurotoxic consequences cannot be overlooked." (PMID 38179375, 2023). "The administration of a methanolic extract of MO to Wistar rats with nephrotoxicity induced by diabetes restored the typical unfavourable side effects caused by streptozotocin (STZ) by lessening the presence of TNF-α and IL-6." (PMID 37570837, 2023). "The increased apoptosis in bone linked to diabetes is significant since inhibiting apoptosis with a caspase-3 inhibitor or a TNF inhibitor results in significantly enhanced tissue formation in diabetic animals." (PMID 37576976, 2023). "We sought lncRNAs that are similarly regulated by HG and TNF-α (2 major factors associated with diabetes known to impair angiogenic function) but divergently regulated by hypoxia (a typical proangiogenic stimulus)." (PMID 36512424, 2023). "It is well established that diabetes is a disorder of inflammation and metabolic dysregulation, associated with increased production of cytokines, including IL-6, IL-1β, and TNF-α." (PMID 38149100, 2023). "LEENE expression was suppressed in cultured ECs treated with diabetes-associated stimuli (e.g., high glucose and TNF-α) in tissues from diabetic mice, and in intima from diabetic human arteries." (PMID 36512424, 2023). "Epidemiologic studies have indicated a positive correlation between the raised plasma level of inflammatory cytokines, such as tumor necrosis factor α (TNF-α) and interleukin-6 (IL-6), with a higher risk of diabetes." (PMID 37298715, 2023). "Diabetes associates with a whole-body low-grade inflammatory status characterized by elevated production of circulating cytokines such as IL-6, TNFα, IFNγ, TGFβ, MCP1, or IL-1b." (PMID 34623540, 2023). "Among the diabetes-associated mechanisms studied, only TNF-α induced significant upregulation of membrane-bound CD40 expression on Müller cells and HRMECs." (PMID 37958563, 2023). "Patients with diabetes mellitus type 2 presented an increase in plasmocytoid dendritic cells in adipose tissue associated with elevated circulating levels of TNF-α." (PMID 36830779, 2023). "It has been reported that there is association between increased TNF-α levels in diabetes and impaired insulin signaling possibly by increasing IRS-1 serine phosphorylation." (PMID 37089941, 2023). "Activated macrophages secrete TNF-α to continuously stimulate liver cells, thereby causing insulin resistance of hepatocytes, and exacerbating the development of metabolic syndrome and diabetes in patients." (PMID 35563076, 2022).
diabetes (continued). "PTGS1 is prostaglandin endoperoxide synthase 1 that activates the prostaglandin pathway, and through TNF alpha signaling, the immune system will be upregulated or downregulated and will cause inflammation in type 2 diabetes mellitus." (PMID 36051390, 2022). "The correlation between TNF-α and nuclear factor kappa B (NF-κB) has been reported in myocardial dysfunction in underlying diabetes." (PMID 35711333, 2022). "The AGE-RAGE signalling pathway in diabetes composition, fluid shear stress and atherosclerosis, TNF signalling pathway, TB, and Kaposi sarcoma linked herpesvirus infection are all included in the KEGG enrichment study." (PMID 35341142, 2022). "We also demonstrated that declined adiponectin (OR = 6.238, P = 0.019) and nesfatin-1 (OR = 2.812, P = 0.01) and elevated TNF-α (OR = 5.541, P = 0.001) were risk factors for prediabetes toward diabetes." (PMID 35311231, 2022). "On the other hand, cytokines of inflammatory such as IL-6 and TNF-α also cause impaired function and damaged kidneys in diabetes." (PMID 35685736, 2022). "Diabetes can increase TNF-α and IL-6 levels, cause the brain’s TJ protein to degrade, aggravate inflammation and leukocyte infiltration, encourage the breakdown of the blood-brain barrier, and ultimately result in cognitive impairment." (PMID 36678547, 2022). "It has also been reported that TNF-α is associated with the development of diabetes and can also alter insulin-mediated glucose uptake in muscle cells in vitro." (PMID 36060470, 2022). "sedentary group is in line with previous studies, which suggested that patients with elevated levels of CRP and pro-inflammatory cytokines such as TNF-α, IL-6 are at increased risk of diabetes, atherosclerosis, hypertension and other cardiovascular diseases." (PMID 36434695, 2022). "Diabetes also has a bidirectional relationship with lean body mass loss through low-grade systemic inflammation, which can be marked by interleukin-6 (IL-6), tumor necrosis factor-alpha (TNF-alpha), C-reactive protein (CRP), and white blood cell count." (PMID 36362539, 2022). "Plasma levels of TNF-a are associated with various risk factors of diabetes such as dyslipidemia, obesity, and inflammation." (PMID 35366956, 2022). "IPA also predicted activation of TNF-α, IL-6, and IL-1β cellular signaling pathways, where these key immunoregulators are known to be associated with diabetes-induced metabolic inflammation." (PMID 35304484, 2022). "Another prospective study of subjects with diabetes showed an association of plasma levels of TNF and ICAM1 with development of PN." (PMID 35651981, 2022). "For example, increased pro-inflammatory factors tumor necrosis factor-α (TNF-α), interleukin-10 (IL-10), and C-reactive proteins (CRPs) lead to an inflammatory response associated with neuropathy in diabetes." (PMID 36313015, 2022). "In the process of skin damage caused by diabetes, AS-IV helps in reducing the levels of TNF-α, promoting the differentiation of macrophages to F4/80+CD206+ M2 macrophages, which accelerates skin wound healing." (PMID 36675720, 2022). "This study indicates that blocking TNF-α improves the metabolic status in obese rats with PD and decreases periodontal breakdown associated with diabetes." (PMID 35547360, 2022). "The same research group also confirmed that anti-TNF-α treatment positively impacts the subgingival microbial profile in rats with diabetes and ligature-induced bone loss." (PMID 35547360, 2022). "Oxidative stress and endoplasmic reticulum stress in diabetes mellitus cause mitochondrial damage that eventually stimulates Fas and TNFα as dearth receptors to set off apoptosis." (PMID 35888150, 2022). "TNF-α rs1800629 polymorphism was significantly associated with the risk of chronic periodontitis, type 2 diabetes mellitus, and celiac disease." (PMID 35888018, 2022).
diabetes (continued). "ChREBP was also associated with up-regulation of several cytokines (TNF-α, IL-1β, and IL-6) in patients with type 2 diabetes mellitus, promoting the inflammatory responses and apoptosis of mesangial cells." (PMID 36741695, 2022). "The underlying mechanisms linking periodontitis and diabetes have been considered to be pro-inflammatory cytokines derived from gingival lesions [tumor necrosis factor alpha (TNF-α), interleukin 6 (IL-6), and IL-17]." (PMID 36299624, 2022). "Interleukin 6 (IL6) and tumor necrosis factor (TNF) are conventional pro-inflammatory cytokines believed to be risk factors for diabetes progression due to their disturbance of insulin signaling." (PMID 36432581, 2022). "ROS produced by mitochondrion are implicated in chronic inflammation, cancer progression, diabetes mellitus, and atherosclerosis, and it also contributes to LPS-mediated production of pro-inflammatory cytokines IL-1β, IL-6, and TNF-α." (PMID 36012352, 2022). "Diabetes has been shown to be an inflammatory process associated with elevated levels of interleukin-1, interleukin-6, C-reactive protein, and tumor necrosis factor-α throughout the body." (PMID 34772392, 2021). "In diabetic patients and rat models, expression of miR-155 in PBMC was also negatively correlated with TNFα, IL-6, and NF-kB activity, which was associated with diabetes complications)." (PMID 33540559, 2021). "In the hyperglycemia-induced oxidative stress and inflammation acute diabetes model, the administration of hyperoside prevented cognitive dysfunction, neuroinflammation, and oxidative stress caused by DM through the TNF-α/NF-κB/caspase-3 signaling pathway." (PMID 34221003, 2021). "TNF-α and IL-6 are important inflammatory factors involved in inflammatory response, often used as diagnostic indicators of diabetes and related complications such as diabetic nephropathy." (PMID 35004803, 2021). "CTRP1 (C1q/TNF-α [tumour necrosis factor-α]-related protein 1), an adiponectin paralog, is associated with diabetes and adverse events in cardiovascular disease." (PMID 34025643, 2021). "The pro-inflammatory cytokine TNF-α was involved in the pathogenesis of diabetes by causing an increase in insulin resistance and a significant elevation in insulin levels in the diabetic microenvironment." (PMID 34975496, 2021). "Evidences from animal model showed that blocking the TNF-α significantly reduced the vascular change induced by diabetes, such as loss of pericyte." (PMID 34434927, 2021). "Diabetes mellitus is associated with high levels of cytokines TNF-α, IL-6, IL-1β, and decreased interferon-γ." (PMID 34926852, 2021). "In the multivariable model including TNF rs1800629 and diabetes, both variables were significantly associated with the CCT (p < 0.001 and p = 0.015)." (PMID 33803434, 2021). "Diabetes also provokes liver fibrogenesis by elevating the production of leptin and TNF-α, which activates the inflammatory pathways that cause hepatic damage and fibrosis." (PMID 33799865, 2021). "Our results shows that odds of heart attack increase by 20 fold if diabetes is associated with high levels of triglycerides, TNFα and IL6 in addition with low levels of HDL-C." (PMID 33510184, 2021). "Large prospective studies and meta-analyses have concluded that anti-TNF therapy improved hyperglycemia or insulin sensitivity and, importantly, reduced lifetime risk of diabetes." (PMID 34616762, 2021). "According to the available studies, fibrinogen, interleukin-6 (IL-6), and tumor necrosis factor-α (TNF-α) are associated with the onset of diabetes." (PMID 34712322, 2021). "The transcription factor YY1 binds allele-specifically to the risk allele of IVS1G + 123A in the tumor necrosis factor α (TNF-α) gene region and increases TNF-α expression and, thereby, diabetes risk." (PMID 33919522, 2021).